ANGPT2 (angiopoietin 2)
Diseases named in the same sentence as ANGPT2 in open-access papers (continued):
Sharing a sentence is not in itself a finding about the gene and the disease.
tumor (continued). "We demonstrate that tumor cell invasion and liver metastasis in SCLC are triggered by an Angiopoietin-2 (ANG-2)/Integrin β-1–dependent pathway in tumor cells, mediated by focal adhesion kinase/Src kinase signaling." (PMID 38775153, 2024). "Studies suggest that the inhibition of ANGPT-2 along with VEGFR-2 improved survival of glioma bearing mice by blocking macrophage recruitment, impairing tumor growth, and prolonging normalization of vessels." (PMID 38213742, 2024). "Additional promising preclinical efficacy was also demonstrated by the combination of ANGPT2/Tie2 inhibitors with anti-VEGF and anti-PD-1 therapy in both genetically engineered and transplant tumor mouse models." (PMID 38339244, 2024). "Another in vitro study confirmed that exogenous supplementation of angiopoietin-2 (ANGPT2), which was another proangiogenic cytokines that sustain tumor angiogenesis, promoted the expression of PD-L1 on M2 polarized macrophages." (PMID 36941554, 2023). "In tumor cells with ITGA5 knockdown, qRT‐PCR and Western Blotting revealed decreased expression of ANGPT1, ANGPT2, and VEGFA, when compared to control cells." (PMID 36999964, 2023). "The HIF pathway also encourages tumor growth by inducing the gene expression of pro-angiogenic factors including VEGF and angiopoietin-2 (Ang-2)." (PMID 37631236, 2023). "Preclinical studies have shown that tumor vascular modulation, driven by the concurrent targeting of VEGFA and ANGPT2, contributes to antitumor immunity through the activation and perivascular accumulation of T cells." (PMID 37843277, 2023). "Angiopoietins, including ANGPT1, ANGPT2, and ANGPT4, have been reported to act as ligands of the tyrosine kinase receptors TIE1 and TIE2 to activate MAPK signaling pathways during tumor angiogenesis in mammals." (PMID 37155312, 2023). "Tumoral lymphangiogenesis is fostered by tumor-derived VEGF-C and other lymphangiogenic growth factors such as angiopoietin 2 and fibroblast growth factor 2, which functionally interact with VEGFR3’s downstream effectors." (PMID 38201272, 2023). "CD34 staining of excised tumour tissue was performed and baseline blood samples were analysed for lactate dehydrogenase (LDH) and angiopoietin-2 (ANGPT-2)." (PMID 36718357, 2023). "The bone marrow niche cells produce angiopoietin-2 (ANGPT2), that destabilize the local endothelium by impairing ANGPT1/Tie2 signaling and promotion of tumor cell survival." (PMID 35150338, 2022). "Tumor macrophages of CSF1Ri-administered animals exhibited significantly lower expression of Il6 and Vegfa (in MC38 model) or Il6 and Angpt2 (in LLC model)." (PMID 35315360, 2022). "Western blot was conducted to evaluate the expression of angiopoietin-2 (ANGPT2), FosB, MS4A4A, and Versican (VCAN) in tumor tissue and normal tissue." (PMID 36569220, 2022). "ANGPT2 also activates TIE2-expressing monocytes/macrophages (TEM), which promote angiogenesis, tumor formation, metastasis, and immunosuppression." (PMID 36172371, 2022). "The results were in accordance with the difference analysis of hub genes (ANGPT2, VCAN, MS4A4A, and FOS) between tumor tissues and normal tissue." (PMID 36569220, 2022). "During tumor progression, the ANGPT switch is considered to be rate-limiting in favor of a higher ANGPT2/ANGPT1 expression ratio." (PMID 36497305, 2022). "Several anti-angiogenic factors, such as angiostatin, endostatin, and angiopoietin 2 (ANGPT2), and the VEGF-A165b isoform modulate inflammatory and tumor angiogenesis." (PMID 35203640, 2022). "The hypoxic tumor microenvironment (TME) leads to the upregulation of vascular endothelial growth factor (VEGF) and angiopoietin 2 (ANGPT2), which are key mediators in angiogenesis." (PMID 36159789, 2022). "Simultaneous infection of stromal and tumor cells; Upregulation of Fez1 and Pycard; Downregulation of DLL-4, Angiopoietin 2, PECAM, Tie-1, and FOS EGR2, CREB-5, IL-6, Map2K1, CCL22, TIMD4 and CCL19." (PMID 35640930, 2022).
tumor (continued). "Of note, primary tumor cultures established from rat and human PitNETs retained the expression of Angpt2/ANGPT2 and Tie2/TIE2 seen in primary tumor tissues." (PMID 35266635, 2022). "The results showed that the expression of ANGPT2, VCAN, and FosB in tumor tissue were higher than normal tissue." (PMID 36569220, 2022). "For instance, Δ9-THC reduced both angiopoietin-2 (Ang-2) and placental growth factor (PIGF) production in tumor cells, whose effect in neoplasms and chronic myeloproliferative diseases is well known." (PMID 34202812, 2021). "It has been reported that many tumor angiogenic factors contribute to the immunosuppressive TME, including vascular endothelial growth factors, angiopoietin 2, placental growth factor, and transforming growth factor-β." (PMID 34294146, 2021). "TIE2-expressing TAMs sense endothelial cell-produced angiopoietin 2 (ANG2), align alongside tumor vasculature, and are critical for de novo angiogenesis and cancer cell dissemination." (PMID 34572013, 2021). "Tumor angiogenesis is regulated by multiple angiogenic factors, such as VEGF-A/VEGFR2, Ang-2, angiopoietin-2/angiopoietin receptor, and DLL4/Notch signaling." (PMID 34358141, 2021). "Angiogenic TAMs are typically located in hypoxic avascular tumor areas with recruitment and maintenance of angiogenic function mediated by CXCL12-CXCR4, angiopoietin-2 (Ang2)-Tie2, and VEGF-VEGFR pathways." (PMID 34988021, 2021). "VEGF (red stars) and angiopoietin-2 (ANG2) (green pentagons) are also produced by these immune cells, which foster both the paracrine and the autocrine VEGF (and/or ANG2) signaling in tumor." (PMID 34149730, 2021). "Studies have shown that another mediator of angiogenesis, angiopoietin 2 (ANG2), in circumstances when VEGF is inhibited, can actually maintain abnormal tumor angiogenesis and thereby overcome anti-VEGF therapy effects." (PMID 34356899, 2021). "Anti-angiogenic strategy aims at inhibiting tumor angiogenesis via blocking pro-angiogenic pathways (e.g. vascular endothelial growth factor (VEGF) pathway and angiopoietin 2(Ang 2) pathway)." (PMID 34930293, 2021). "After recruitment to the TME, TAMs release different factors—such as VEGF, IL-6, Angiopoietin 2 (ANG2), and insulin-like growth factor-binding protein 1 (IGFBP1)—to stimulate neovascularization in the tumor." (PMID 34503065, 2021). "The results indicated that the expression of tumor cell-derived VEGFA, IGFBP3, EFNA1, EFNB1, IGF2, PDGFA and stroma-derived Angpt2, Cdh5, Esam, Esm1, Icam2, and Tie1 was statistically correlated with that of Pecam1 and elevated in p-EMT TW2.6 tumors." (PMID 34869001, 2021). "Other tumor biomarkers have been proposed such as osteopontin (OPN), vascular endothelial growth factor (VEGF), angiopoietin 2 (ANG-2), Golgi protein 73 (Gp-73), insulin growth factor-1 (IGF-1), hepatic growth factor (HGF), Glypican-3 and c-MET among others." (PMID 32492896, 2020). "For example, VEGF, PLGF, MMP‐10, MMP‐3, Angpt2, and PTHLH released from tumor cells in various types of tumors are capable of triggering pulmonary endothelium hyper‐permeability, thereby accelerating extravasation of tumor cells." (PMID 33252861, 2020). "We also found that the expression of these 5 genes, namely, ANGPT2, EMCN, GLDN, USHBP1 and ZNF532, was significantly upregulated in HCC tumor tissues compared to the adjacent normal liver tissues in the TCGA and ICGC datasets." (PMID 32644941, 2020). "The expression of ANGPT2, GLDN, and ZNF532 was significantly higher in the 268 HCC tumor tissues of the GSE25097 dataset compared to the 243 non-tumor liver tissue samples (p < 0.001)." (PMID 32644941, 2020). "Nevertheless, the expression of ANGPT2, EMCN and ZNF532 genes was significantly higher in the HCC tumor samples compared to the normal liver tissue samples." (PMID 32644941, 2020).
tumor (continued). "ANGPT2 and VEGFA have complementary roles in regulating tumor angiogenesis and synergistic effect on survival, suggesting that dual pathway inhibition is necessary to improve treatment outcomes." (PMID 31892982, 2020). "Previous research has demonstrated that VEGF-A and angiopoietin 2 (ANGPT2) are critical players in tumor angiogenesis, while VEGF-A has been considered the primary factor driving the expansion of the tumor angiogenesis." (PMID 33330077, 2020). "VEGF-A was shown to increase the expression of ANGPT-2 in endothelial cells via the NFAT pathway, thereby leading to tumor lymphangiogenesis and lymph node metastasis in mice with pancreatic and lung tumors." (PMID 33172072, 2020). "Another study observed that the expression of angiopoietin-1 and angiopoietin-2 was upregulated in HCC patients and correlated with tumor dedifferentiation and tumor vascularity." (PMID 30959975, 2019). "Among the top differentially expressed genes between tumor and DTC samples, we found genes involved in metastasis initiation and angiogenesis, for example, MGP, BGN, POSTN and ANGPT2, to be upregulated in tumors." (PMID 28921546, 2018). "It has been shown that VEGF mRNA expression was mainly targeted to primary colorectal tumor cells whereas angiopoietin-2 and HGF mRNA expression was targeted to tumor-adjacent stromal cells." (PMID 30598022, 2018). "Hsa-miR-542-3p acts as tumor suppressor by targeting survivin (BIRC5), the oncogene astrocyte-elevated gene-1 (MTDH), or angiopoietin-2 (ANGPT2) that plays a role in tumor angiogenesis." (PMID 29293623, 2018). "TNF, IL6 and ANGPT2 were expressed equally by both DLD1 and SKBR7 xenografts, whereas higher levels of IL1B, IL4, IL13 and VEGFA were found in DLD1 tumours." (PMID 29367702, 2018). "Once inside the tumor, TIE2+ macrophages bind to angiopoietin-2 (Ang-2) expressed by endothelial cells and stimulate the growth of blood vessels promoting tumor growth and metastasis." (PMID 30356656, 2018). "As for angiogenesis process, miR-218 overexpression significantly suppressed the protein levels of VEGFA and ANGPT2 in SW620 and HCT116, which play important role in tumor angiogenesis." (PMID 29977158, 2018). "Although our results demonstrate ADAM9 proteins regulate VEGFA and ANGPT2 expression regardless protease activity, shedding function of ADAM9 is still important for pro-angiogenic factors generation to promote tumor growth." (PMID 29118335, 2017). "Tumour cells of the angiogenic phenotype displayed higher levels of hypoxic (HIF1α, HIF2α, MCT4) and angiogenic markers (VEGF, ANGPT2)." (PMID 27049916, 2016). "Apart from VEGF, HIF-1α, and TGF-α, angiopoietin-2 (Ang-2), a ligand of the Tie2 tyrosine kinase receptor, has also been reported to be involved in TAM-regulated angiogenesis in tumor microenvironment." (PMID 27191744, 2016). "Expression of endothelial and mesenchymal markers (ANGPT2, CHI3L1) indicated a stronger contribution of the micro-environment to the manifestation of the mesenchymal subtype than the tumor biology itself." (PMID 26673168, 2015). "This suggests that the sMSC-derived ANGPT2 and CCL2 play a key role in the sMSC-induced tumor growth." (PMID 25883937, 2015). "We found that the sMSCs prepared either in vitro or in vivo specifically produce ANGPT2, CCL2, CCL3, and FSTL1, and most powerfully affect tumor behavior and host immunity by using these molecules (unpublished data except CCL2)." (PMID 25883937, 2015). "The specific overexpression of EFNB2 in small tumours with lymphatic spread and the typical decrease of the ANGPT1/ ANGPT2 ratio in larger tumours give weight to EFNB2 and angiopoietins as prognostic factors and potential therapeutic targets." (PMID 26044849, 2015). "ANGPT2, in general, acts as ANGPT1-Tie antagonist and exerts anti-angiogenic effects in several tumour entities." (PMID 26044849, 2015). "EFNB2, ANGPT2, and VEGF were overexpressed in 84 % to 98 % of the tumour samples with an average expression factor of 2.3 to 4.5." (PMID 26044849, 2015).
tumor (continued). "Disrupting the interaction between ANGPT2 and its TIE2 receptor suppressed tumor growth and angiogenesis." (PMID 25811856, 2015). "Tumours with lymphatic spread showed higher gene expression rates of VEGFA, EFNB2 and ANGPT2 in moderately differentiated tumours and of VEGFA and EFNB2 in small tumours, respectively." (PMID 26044849, 2015). "Tumor endothelium releases angiopoietin-2 and further facilitates recruitment of TIE2 receptor expressing monocytes (TEM) into tumor sites." (PMID 24634660, 2014). "Of these, angiopoietin 2 (ANGPT2), protocadherin 12 (PCDH12) and leucine rich repeat containing 8 family member C (LRRC8C) had expression profiles completely restricted to tumour or foetal tissues." (PMID 18394197, 2008). "MVI Endo engaged in robust VEGF, ANGPT2, and TGF-β signaling with tumor and stromal cells." (PMID 41993588, 2026). "Due to the complex cellular elements within the tumor, the expression of ANGPT2, Tie2, and VEGF-A are not limited to a specific type of cell." (PMID 40370455, 2025). "Vascular remodeling, driven by tumor-secreted pro-angiogenic factors like vascular endothelial growth factor (VEGF) and angiopoietin-2, induces the formation of abnormal, highly permeable blood vessels that enhance the dissemination and survival of tumor cells." (PMID 40909970, 2025). "More critically, this paper, for the initial time, elaborates that IFN-γ modulates the expression of ANGPT2 and Tie2 via the AKT-FOXO1 and JAK1/2-STAT1 pathways, thereby providing direct evidence for the normalization of tumor vascular structures regulated by IFN-γ in immunotherapy." (PMID 40370455, 2025). "Notably, IFN-γ was shown to suppress the mRNA expression of ANGPT2 and TEK in HUVECs and HPMECs and to inhibit the mRNA expression of VEGF-A in tumor cells." (PMID 40370455, 2025). "Another mechanism of resistance is attributed to the activity of alternative proangiogenic pathways, such as fibroblast growth factor (FGF) and angiopoietin-2 (ANGPT2), which can promote the creation of new blood vessels that will vascularize the tumor, resulting in its progression." (PMID 40002260, 2025). "For example, angiopoietin-2 (Ang-2), a ligand of the endothelial tyrosine kinase Tie-2, increased microvessel density and lymphatic metastasis, but did not affect primary tumor growth." (PMID 40565098, 2025). "Moreover, ECs secrete ANGPT1 and ANGPT2, which effectively bind to the TIE2‐R, disrupting the adhesion complex between PCs and ECs and thereby regulating angiogenesis within tumours." (PMID 40268524, 2025). "In addition, there is a stimulating effect of Hyperin on the production of angiopoietin-2 (ANG-2) and therefore on angiogenesis which, in turn, is a mechanism necessary for tumor growth." (PMID 39457728, 2024). "Moreover, preclinical investigations have proven that the dual neutralization of ANGPT2 and VEGF altered tumor vasculature effectively and contributes to enhanced anti-tumor immunity." (PMID 39107856, 2024). "Interestingly, for the used treatment temperatures, the intracellular HIF-1α accumulation in tumor cells seems to play a role in MAPK/ERK activation and mediator secretion (e.g., VEGF, PDGF-AA, Angiopoietin-2), as shown by inhibition experiments." (PMID 37626752, 2023). "It is generally believed that ANGPT2, as an antagonist of ANGPT1, competitively binds to its specific tyrosine kinase receptors-2 (Tie-2) receptors and blocks the vascular-stabilizing effect of Ang-1, leading to sustained neovascularization in tumor tissues." (PMID 36907878, 2023). "Dual blocking of ANGPT2 and VEGFR2 effectively impaired glioma progression, promoted vascular normalization, blocked macrophage recruitment, and prolongered the prognosis of tumor-bearing mouse models." (PMID 36959862, 2023). "While anti-ANGPT2 treatment did not alter the density of CD8+ T cells in either the tumor periphery or the tumor core at 18 weeks, it significantly enhanced the infiltration of CD8+ T cells into both these areas by 20 weeks." (PMID 37843277, 2023).
tumor (continued). "Interestingly, while both Angpt2 and VEGF promote angiogenesis, these growth factors have distinct functions in tumor angiogenesis and metastasis." (PMID 35884919, 2022). "This “oxygenation heterogeneity” was later confirmed by studies using chemical oxygen probes and the detection of transcripts or proteins induced by hypoxia at the particular tumour areas (e.g., CA9, VEGF, ANGPT2, EPAS1), with the rest of the tumour being relatively well-oxygenated." (PMID 36230775, 2022). "Univariate analysis revealed that higher pathological N status according to AJCC tumor-node-metastasis (TNM) classification was significantly correlated with higher CCL4 and ANGPT2 expression; only ANGPT2 expression was positively correlated with pathological T status." (PMID 35884919, 2022). "Interestingly, a subcluster of Endo-1 was found almost exclusively in the tumor compartment, preferentially expressing known endothelial tip cell genes (KCNE3, DLL4, EDNRB, ANGPT2, and SERPINE1)." (PMID 36180422, 2022). "Inhibition of ANGPT2 and VEGF has a cumulative effect on tumour growth and angiogenesis." (PMID 36578083, 2022). "Albeit staining tumor tissues with anti‐P‐Tie2 antibodies has technical limitations, we found that P‐Tie2 and Angpt2 co‐localize in the tumors, whereas in adjacent non‐tumor areas Angpt2‐positive pituitary cells do not express P‐Tie2 (Fig EV3)." (PMID 35266635, 2022). "The CM of primary tumor cells significantly increased the proliferation of both scRNA‐ and siAngpt2‐GH3 cells (+60% and +57% versus medium alone, respectively; P < 0.0001), although silencing Angpt2 suppressed cell proliferation, as expected (Fig EV2)." (PMID 35266635, 2022). "We therefore hypothesized that ANGPT2 might be regulated by biglycan/TNF-α signaling, leading to the destabilization of tumor blood vessels." (PMID 33966638, 2021). "In PCa, intraductal grown tumor cells express angiopoietin-1 but not angiopoietin-2 while in the blood vessels close to the ducts, apical tumor cells express angiopoietin-1 and Tie-2." (PMID 33841508, 2021). "Interestingly, STMN1 and ANGPT2 were significantly positively correlated with tumor purity, whereas RAP1A, FLT3, HSPA8, and PGF were all significantly negatively correlated with tumor purity." (PMID 34178637, 2021). "ANGPT2 interaction with its receptor TIE2 increases the infiltration of neutrophils and promotes its adhesion, in addition to TIE2-expressing monocytes, to the tumor endothelium." (PMID 34359588, 2021). "While the CD34 (endothelial neo-angiogenesis marker) expression increased with tumor progression (PCC +1.8-fold, p= 0.0003; advanced PCC +3.3-fold, p = 0.004), Vegfa was elevated only in advanced PCCs (+2.4-fold, p = 0.0121) and Angpt2 only in early-stage PCCs (+5.2-fold, p = 0.0003)." (PMID 33401758, 2021). "In addition there are other molecules that affect angiogenesis, such as angiopoietin-2 (ANG-2), fibroblast growth factors (FGF), and chemokines, released by hypoxic, inflammatory, or tumor cells." (PMID 33562561, 2021). "We hypothesized that proangiogenic factors such as angiopoietin-1 (ANG-1) and angiopoietin-2 (ANG-2), two targetable cytokines, might play a role in tumor development and metastatic behavior." (PMID 34439141, 2021). "Moreover, the significant downregulation of ANGPT2, ANGPT2, ANGPTL1, ANGPTL4, and ANGPTL6 was found in tumor-adjacent tissues." (PMID 34685578, 2021). "In addition, alternative pro-angiogenic signaling pathways including ANGPT-2, FGF-2, IL-8 can be induced by tumor cells in response to a pharmacological inhibition of the VEGF signaling pathway." (PMID 31690961, 2020). "Indeed, simultaneous ANGPT-2 and VEGFR2 inhibition impairs tumor growth, prolong vessel normalization and blocks macrophage recruitment improving survival of glioma bearing mice." (PMID 31690961, 2020). "Analysis conducted on SQC patients also showed no statistical difference among the protein expressions of ANGPT2 and the different lymph node status, tumor grade." (PMID 31892982, 2020).